FTO (FTO alpha-ketoglutarate dependent dioxygenase)
Diseases named in the same sentence as FTO in open-access papers (continued):
Sharing a sentence is not in itself a finding about the gene and the disease.
melanoma (continued). "It is generally believed that inhibiting the combination of FTO and anti-PD-1 blockade may attenuate the resistance of melanoma to immunotherapy and improve the treatment response." (PMID 35069586, 2021). "Moreover, depletion of FTO expression by shRNA enhanced melanoma cell sensitivity to anti-PD-1 antibody." (PMID 34076564, 2021). "Therefore, co-targeting FTO in combination with ICB-antibodies would be a promising approach to control melanoma progression." (PMID 34571899, 2021). "FTO has a similar antitumor effect on melanoma as a factor in anti-PD-1 resistance." (PMID 34531875, 2021). "FTO, prompted by metabolic stress and starvation through the NF-κB signaling pathway and autophagy, increases melanoma growth and decreases response to anti-PD-1 blockade immunotherapy by protecting tumor cell-intrinsic genes (PD-1 (PDCD1), CXCR4 and SOX10) mRNA from decaying." (PMID 34526985, 2021). "As a demethylase, FTO has been shown to promote the development of melanoma." (PMID 33777035, 2021). "Theoretically, targeted overexpression of Mettl-3 might also control melanoma progression by decreasing FTO via balancing mechanism, and also by directly inhibiting the expression of pro-tumorigenic genes via recruiting YTHDF2 reader proteins." (PMID 34571899, 2021). "Therefore, one promising strategy is to combine FTO inhibition with anti-PD1 blockade for reducing the resistance to immunotherapy in melanoma." (PMID 34900983, 2021). "Therefore, FTO depletion sensitizes melanoma cells to interferon gamma (IFNγ) and anti-PD-1 treatment in mice." (PMID 33611339, 2021). "In addition, in melanoma, some studies have found that demethylase FTO can promote the growth of melanoma." (PMID 34737950, 2021). "Demethylase FTO significantly promoted melanoma tumorigenesis and decreased response to anti-PD-1 blockade immunotherapy, suggesting that FTO inhibition combined with anti-PD-1 blockade may sensitize immunotherapy in melanoma." (PMID 35069534, 2021). "In addition, FTO level was found to be increased in human melanoma, knockdown of which increases m6A methylation in PD-1, CXCR4, and SOX10, leading to increased RNA decay through the m6A reader YTHDF2." (PMID 33611339, 2021). "In addition, FTO knockouts make melanoma cells sensitive to interferon gamma (IFN γ), thereby increasing the sensitivity of mouse melanomas to PD-1 monoclonal antibody treatment." (PMID 33926508, 2021). "FTO plays a crucial role in therapeutic resistance to anti-PD1 immunotherapy in melanoma." (PMID 34900983, 2021). "However, in melanoma, FTO was up-regulated in response to metabolic stress and promoted adaptation to metabolic stress, therefore reflecting the context-dependent roles of m6A in response to metabolic stress." (PMID 33669361, 2021). "However, FTO knockout increases MA methylation in the critical pro-tumorigenic genes and makes melanoma cells sensitive to Anti-PD-1 treatment in mice." (PMID 33344447, 2020). "FTO played a crucial role by promoting melanoma tumorigenesis and anti-PD-1 resistance." (PMID 33304380, 2020). "To determine whether regulation of these melanoma-promoting genes by FTO is m6A-dependent, we assessed the role of m6A by knocking down the m6A methyltransferases METTL3 and METTL14." (PMID 31239444, 2019). "FTO can be upregulated by metabolic stress and starvation, a metabolic challenge that tumor cells are constantly facing in vivo, suggesting that the induction of FTO serves as an adaptive mechanism to metabolic stress in melanoma cells to promote proliferation, invasion, and migration." (PMID 31239444, 2019). "Next, we investigated whether FTO knockdown sensitizes melanoma cells to cell death induced by IFNγ." (PMID 31239444, 2019). "We found that FTO inhibition enabled an anti-melanoma response to anti-PD-1 immunotherapy in mice." (PMID 31239444, 2019).
melanoma (continued). "Our findings may provide new opportunities for developing improved melanoma therapies by inhibiting the FTO pathway in combination with anti-PD-1 immunotherapy." (PMID 31239444, 2019). "It appears that the melanoma intrinsic FTO pathway is not only critical for melanoma malignant traits and tumorigenicity in immunocompromised hosts, but also crucial for promoting resistance to IFNγ-induced killing in vitro and anti-PD-1 blockade in immunocompetent hosts in vivo." (PMID 31239444, 2019). "Second, we found that metabolic stress and starvation induces FTO expression in melanoma cells." (PMID 31239444, 2019). "However, the role of FTO as an m6A eraser in melanoma pathogenesis and response to anti-melanoma therapies remains poorly understood." (PMID 31239444, 2019). "We found that FTO plays a crucial role in metabolic pathways in melanoma cells." (PMID 31239444, 2019). "FTO is increased in melanoma, suggesting a protumorigenic role of FTO in melanoma." (PMID 31239444, 2019). "To understand the mechanism by which FTO inhibition sensitizes melanoma to anti-PD-1 blockade, we first analyzed whether FTO knockdown affects T cell infiltration into tumors after PD-1 blockade." (PMID 31239444, 2019). "Indeed, anti-IFNγ antibody increased melanoma tumor growth in both control and FTO-knockdown cells in mice." (PMID 31239444, 2019). "Our findings demonstrate that melanoma genes are regulated by FTO through m6A RNA methylation." (PMID 31239444, 2019). "Furthermore, we found that overexpression of PD-1 (PDCD1), CXCR4, or SOX10 inhibited IFNγ-induced cell death in FTO-knockdown melanoma cells." (PMID 31239444, 2019). "It is possible that FTO induced by starvation promotes melanoma cell proliferation and/or survival." (PMID 31239444, 2019). "Next we analyzed the role of FTO in the response of melanoma cells to IFNγ." (PMID 31239444, 2019). "FTO level is increased in human melanoma and enhances melanoma tumorigenesis in mice." (PMID 31239444, 2019). "Furthermore, knockdown of METTL3 and METTL14 prevented the effect of FTO knockdown on cell growth/proliferation, migration, invasion, and cell viability in melanoma cells in suspension." (PMID 31239444, 2019). "Moreover, comparison of the porcine results to those reported by human melanoma GWAS indicated shared association signals notably at CDKAL1 and TERT loci but also nearby CCND1, FTO, PLA2G6 and TMEM38B-RAD23B loci." (PMID 29963229, 2018). "Out of 20 orthologues of human melanoma-associated loci, 12 contained SNPs with p-values < 10–2 in the MeLiM model, and 6 of them had SNPs reaching a p-value < 10–3: CDKAL1 on SSC7, FTO on SSC6, PLA2G6 on SSC5, TMEM38B-RAD23B on SSC1 and SLC45A2 and TERT on SSC16." (PMID 29963229, 2018). "Hence, combining FTO inhibitors with anti-PD-1 monoclonal antibodies may resensitize melanoma to immunotherapy." (PMID 40483535, 2025). "It has been shown that the eraser FTO acts as an m6A demethylase to promote melanoma tumorigenesis and induce resistance of tumor cells to anti-PD-1 therapy, and moreover, the combination of FTO inhibition and anti-PD-1 blockade may synergistically reduce melanoma resistance to immunotherapy." (PMID 35265626, 2022). "In melanoma, FTO could not only promote tumor progression but also lead to anti-PD1 resistance." (PMID 35331183, 2022). "They identified specific FTO-mediated and m6A-mediated mechanisms that contribute to the development of melanoma and resistance to anti-PD-1 blockade, and they also demonstrated that the combination of FTO inhibition and anti-PD-1 blockade reduced resistance and improved anti-melanoma responses." (PMID 33673851, 2021). "Importantly, a small-molecule ALKBH5 inhibitor enhanced the efficacy of cancer immunotherapy in melanoma, suggesting that the combination of FTO/ALKBH5 inhibition with anti-PD-1 blockade may reduce the resistance to immunotherapy in melanoma." (PMID 34526985, 2021). "In addition, FTO plays a crucial role in promoting melanoma anti-PD-1 resistance." (PMID 34248650, 2021).
melanoma (continued). "Additionally, knockout of FTO sensitizes mouse melanomas to anti-PD-1 treatment." (PMID 34858499, 2021). "Ultimately, however, they suggest that the regulation of these melanoma-promoting genes by FTO and other proteins might critically affect gene expression in melanoma (e.g., the methyltransferases METTL3 and METTL14) and further studies on the therapeutic potential of such are warranted." (PMID 34105069, 2021). "Moreover, silencing of FTO sensitized melanoma to anti-PD-1 treatment." (PMID 32733807, 2020). "Additionally, the FTO was identified as a pro-tumorigenic factor in melanoma." (PMID 33511112, 2020). "Our results identify a unique FTO-mediated and m6A-mediated mechanism in promoting melanoma tumorigenesis and resistance to anti-PD-1 blockade, and suggest that the combination of FTO inhibition with anti-PD-1 blockade may reduce resistance and improve the anti-melanoma response." (PMID 31239444, 2019). "Furthermore, FTO knockdown sensitized melanoma to anti-PD-1 blockade." (PMID 31239444, 2019). "Next we investigated whether these melanoma-promoting genes are responsible for FTO’s function." (PMID 31239444, 2019). "Our findings demonstrate a crucial role of FTO as an m6A demethylase in promoting melanoma tumorigenesis and anti-PD-1 resistance, and suggest that the combination of FTO inhibition with anti-PD-1 blockade may reduce the resistance to immunotherapy in melanoma." (PMID 31239444, 2019). "Therefore, inhibiting the FTO pathway in melanoma may provide a new opportunity to reduce resistance to anti-PD-1 immunotherapy." (PMID 31239444, 2019). "However, at least for FTO, the association with melanoma was independent of the body mass index association signal." (PMID 29963229, 2018). "A recent study demonstrated that FTO stimulates the glycolytic activity of tumor cells, thus modulating CD8+ T-cell function and promoting melanoma development." (PMID 41184232, 2025). "Silencing of FTO further sensitized melanoma cells to IFN-γ and enhanced the response of melanoma to anti-PD-1 treatment in murine models." (PMID 39987091, 2025). "Considering FTO's role in the TME remodelling and its involvement in immune surveillance, co‐culturing Dac51‐pretreated B16OVA melanoma cells with T cells demonstrated enhanced cytokines release and elevated cytotoxic capacity." (PMID 38545841, 2024). "The use of FTO inhibitors in HCC and melanoma can enhance immune activation and sensitivity to anti-PD-1 treatment." (PMID 39372415, 2024). "Preclinical models of melanoma and CRC reveal synergism between FTO inhibition and anti‐PD‐1 therapy." (PMID 38545841, 2024). "In melanoma, knockdown of FTO promotes YTHDF2-mediated PD-1, CXCR4, and SOX10 mRNA decay, sensitizing melanoma cells to interferon-gamma and anti-PD-1 therapy." (PMID 36859310, 2023). "For immunotherapy, another inhibitor Dac5 relived the constraints on T cells activation and functions imposed by FTO, which improves the ICB efficacy in melanoma." (PMID 36810281, 2023). "Several m6A regulators including METTL3, YTHDF1, HNRNPA2B1, FTO, and IGF2BP3 are involved in melanoma." (PMID 37124930, 2023). "In melanoma cells 87, metabolic stress conditions, such as a model starvation medium (Hank's Balanced Salt Solution, HBSS), increased FTO mRNA and protein levels, accompanied by a decreased m6A level." (PMID 36632456, 2023). "The demethylases, FTO and ALKBH5 reduce the response to anti-PD-1 blockade and accelerate melanoma tumorigenesis by reducing m6A methylation of critical protumorigenic melanoma cell-intrinsic genes." (PMID 35090469, 2022). "For example, in melanoma, FTO expression reduces the methylation of SOX10, CXCR4, and PD-1 by m6A in key tumor-promoting melanoma cell-intrinsic genes to promote tumorigenesis." (PMID 36360287, 2022). "FTO knockdown increases m6A modification of PD-1 (PDCD1), CXCR4, and SOX10, contributing to enhanced RNA decay via the m6A reader YTHDF2 in melanoma cells." (PMID 36071523, 2022).
melanoma (continued). "For example, in melanoma, all of METTL3/14, ALKBH5 and FTO can modulate tumor response to anti-PD-1 therapy in mice." (PMID 35590394, 2022). "We then investigated the expression of common methyltransferases and demethylases like METTL3, METTL14, FTO and ALKBH5 in three melanoma cell lines, which demonstrated that the process of m6A modification was available in melanoma cell lines." (PMID 36324258, 2022). "In melanoma, FTO is induced by metabolic starvation through autophagy, whereas knockdown of ATG5 or ATG7 in turn attenuates the expression of FTO." (PMID 35159248, 2022). "It has been reported that the m6A eraser FTO is upregulated by metabolic stress (serum starvation and HBSS treatment) and plays a pro-tumorigenic role in melanoma cells." (PMID 34373753, 2021). "In melanoma cells, YTHDF2 would serve as a tumor suppressor, mediating the downregulation of the FTO target genes." (PMID 34105069, 2021). "In addition, FTO might decrease the response to anti-PD-1 blockade immunotherapy in melanoma." (PMID 34248650, 2021). "In melanoma cells, IFN-γ downregulates FTO, and FTO promotes resistance to IFN-γ-mediated killing through its m6A demethylase activity and downstream targets PD-1 (PDCD-1), CXCR4, and SOX10." (PMID 34858499, 2021). "In melanoma, FTO promoted the expression of PDCD1, which expresses the PD-1 protein, as well as CXCR4 and SOX10, promoting melanoma tumorigenesis and resistance to immunotherapy." (PMID 33669361, 2021). "Depleting FTO promotes the degradation of downstream genes PD-1, CXCR4, and SOX10 in an m6A-dependent manner, thereby sensitizing patients with melanoma to anti-PD-1 checkpoint blockade therapy." (PMID 33292526, 2020). "Next, we determined the FTO protein levels in normal human epidermal melanocytes (NHEM) and a panel of melanoma cell lines." (PMID 31239444, 2019). "Notably, genetic knockout of FTO in melanoma cells resulted in a marked increase in CD4 + tumor-infiltrating lymphocyte (TIL) numbers and IFN-γ production in B16F10 melanoma following anti-PD-1 blockade." (PMID 39987091, 2025). "For eraser genes, studies have found that knocking down FTO in mouse models could increase the tumor’s sensitivity to PD-1 therapy, while ALKBH5 promoted melanoma cell proliferation, migration, and invasion by acting on FOXM1 and ABCA1." (PMID 41301778, 2025). "However, it was demonstrated that FTO knockdown triggers the m6A hypermethylation and increases RNA decay via YTHDF2 (m6A reader), moreover, it sensitizes melanoma cells to IFN and anti-PD-1 therapies." (PMID 40427015, 2025). "Furthermore, FTO knockdown increases YTHDF2-mediated m6A modification of oncogenes, including PD-1, CXCR4 and SOX10, and sensitizes melanoma cells to IFN-γ and anti-PD-1 treatment." (PMID 36810108, 2023). "Mechanistically, FTO overexpression promoted melanoma development by increasing the key oncogenic genes (PD-1, CXCR4 and SOX10) in mRNA and protein levels and SOX10, and inhibiting IFN-γ-induced melanoma cell death." (PMID 37264402, 2023). "Moreover, FTO functionally increased the expression of heat shock factor 1 (HSF1), a reported metastasis-promoting gene in melanoma, which facilitated the proliferation, migration, and invasion of MM cells." (PMID 35628623, 2022). "Also, knockdown of FTO markedly improves cell sensitivity to interferon (IFN)-γ and anti-PD-1 therapeutics in melanoma, which suggested a promising anticarcinogenic therapy." (PMID 34446007, 2021). "Of interest, the increased m6A methylation of important oncogenes in FTO knockdown cells also promoted YTHDF2-induced degradation in melanoma, whereas melanoma cells appear to be more sensitive to IFN-γ and enhance the efficacy of melanoma immunotherapy." (PMID 33692959, 2021). "The PD-1 blockade increased CD4+ tumor-infiltrating lymphocyte (TIL) numbers in B16F10 melanoma with FTO knockdown, but not in control cells." (PMID 31239444, 2019).
melanoma (continued). "To determine whether FTO inhibition affects immunotherapy response, we treated C57BL/6 mice bearing B10F10 melanomas with anti-PD-1 antibody or isotype control IgG." (PMID 31239444, 2019). "FTO mediating PKM2 demethylation so as to promote the tumorigenesis and development of liver cancer 41, 46.Another study demonstrated that FTO could promote melanoma tumorigenicity both in human and mice." (PMID 34345203, 2021). "However, FTO knockdown in melanoma cells did not affect the number of IFNγ-producing CD4+ or CD8+ TILs s." (PMID 31239444, 2019). "Since FTO promotes melanoma tumorigenicity and regulates the expression of tumor-promoting melanoma cell-intrinsic PD-1 as well as CXCR4 and SOX10, we reasoned that FTO may also regulate the response of melanoma to immunotherapy." (PMID 31239444, 2019).